TRAV7 (T cell receptor alpha variable 7)
Description:
V region of the variable domain of T cell receptor (TR) alpha chain that participates in the antigen recognition. Alpha-beta T cell receptors are antigen specific receptors which are essential to the immune response and are present on the cell surface of T lymphocytes. Recognize peptide-major histocompatibility (MH) (pMH) complexes that are displayed by antigen presenting cells (APC), a prerequisite for efficient T cell adaptive immunity against pathogens. Binding of alpha-beta TR to pMH complex initiates TR-CD3 clustering on the cell surface and intracellular activation of LCK that phosphorylates the ITAM motifs of CD3G, CD3D, CD3E and CD247 enabling the recruitment of ZAP70. In turn ZAP70 phosphorylates LAT, which recruits numerous signaling molecules to form the LAT signalosome. The LAT signalosome propagates signal branching to three major signaling pathways, the calcium, the mitogen-activated protein kinase (MAPK) kinase and the nuclear factor NF-kappa-B (NF-kB) pathways, leading to the mobilization of transcription factors that are critical for gene expression and essential for T cell growth and differentiation. The T cell repertoire is generated in the thymus, by V-(D)-J rearrangement. This repertoire is then shaped by intrathymic selection events to generate a peripheral T cell pool of self-MH restricted, non-autoaggressive T cells. Post-thymic interaction of alpha-beta TR with the pMH complexes shapes TR structural and functional avidity.
Synonyms: TCRAV7S1
Gene: T-cell receptor variable (V) gene on chromosome 14 (21,782,993 to 21,783,503, forward strand). Ensembl gene ENSG00000211781.
Subcellular location: Cell membrane
Gene Ontology:
Biological process: response to bacterium
Cellular component: plasma membrane
Homologues: Paralogues in human: TRAV20 (54% identical), TRAV17 (46% identical), TRAV10 (45% identical), TRAV24 (42% identical), TRAV39 (42% identical), TRAV13-1 (41% identical), TRAV21 (41% identical), TRAV36DV7 (41% identical), TRAV6 (38% identical), TRAV27 (35% identical), TRAV5 (35% identical), TRAV13-2 (34% identical), and 11 more.